INS (insulin)
Diseases named in the same sentence as INS in open-access papers (continued):
Sharing a sentence is not in itself a finding about the gene and the disease.
Obesity (continued). "MicroRNAs have been associated with many of these PCa-related risk factors, including insulin secretion and insulin resistance, glucose and lipids in blood, prediabetes, obesity and type 2 diabetes." (PMID 34298752, 2021). "Abundance of Phascolarctobacterium and Dialister has been associated with insulin sensitivity (positively and negatively, respectively) in individuals with obesity, as measured by the hyperinsulinemic–euglycemic clamp technique." (PMID 34579172, 2021). "Chronic elevated free fatty acids (FFAs) in blood plasma impair insulin-associated glucose transport, uptake, and utilization in hepatocytes, adipocytes, and skeletal myocytes both in obesity as well as T2DM." (PMID 35221617, 2021). "Although weight loss associates with improved insulin sensitivity in the context of obesity, a key point is that the effective and potentially chronic improvement of IR can occur simply through the adoption of a healthy lifestyle." (PMID 33430419, 2021). "In obesity conditions, skeletal muscle is infiltrated with lipids, causing a reduction in its fatty acid β-oxidation and altering its insulin sensitivity." (PMID 33806797, 2021). "The decreased level of adiponectin and increased levels of leptin, c-peptide, insulin and angiopoietin-like 3 protein were associated with metabolically healthy and unhealthy obesity." (PMID 34947881, 2021). "miR-26a is a well conserved miRNA whose overexpression or inhibition has been implicated in the pathogenesis of multiple disease, including obesity associated comorbidities such as reduced insulin sensitivity and atherosclerosis." (PMID 34690698, 2021). "The transcriptional coregulatory protein PRDM16 is required for beige fat activation, which is associated with protection from obesity and improved insulin sensitivity." (PMID 33220490, 2021). "NAFLD is defined as the excess accumulation of fat in the liver and tightly associated with the obesity, T2D, MS, insulin, and dyslipidemia." (PMID 33632126, 2021). "In the current study, we observed stronger and more pronounced associations of cognitive functions with HOMA-IR, insulin, and HbA1c among adults with BMI < 30 kg/m2 compared with those with obesity." (PMID 34966358, 2021). "A positive association is also detected between insulin and obesity-prone cancers in terms of tumor growth in rodents as well as stage at diagnosis and death in humans." (PMID 33987528, 2021). "Results after a 6-month period on an LCKD in women with PCOS and obesity showed a significant improvement in fasting insulin, which appeared to be the cause of LH/FSH ratio enhancement." (PMID 34071499, 2021). "Skeletal muscle resistance to insulin is fundamental to the metabolic dysregulation associated with obesity and physical inactivity, contributing to the development of the metabolic syndrome." (PMID 33765000, 2021). "It is known that inflammatory changes in fetal adipose tissue and skeletal muscles of fetuses from mothers with obesity can cause excessive insulin production by the pancreas and insulin resistance." (PMID 33669686, 2021). "Previous studies in animal models and in humans have shown that obesity associates with high levels of Lactobacillus and Lactococcus genera, which also positively correlated with fasting plasma insulin." (PMID 34943104, 2021). "In recent years, the influence of exercise training on the dysbiotic gut microbiota associated with obesity and insulin resistance has also been investigated." (PMID 33870263, 2021). "Even brief increases in food consumption lead to immediate increases in insulin levels, and permanently elevated insulin levels have been shown to be associated with weight gain and obesity." (PMID 33922802, 2021). "The association of body fat with bone parameters, TOC, insulin, and adiponectin seem to be more sex-specific when body fat measurements with higher accuracy are used instead of BMI alone to classify obesity." (PMID 35010988, 2021).
Obesity (continued). "Insulin resistance (IR, defined as the inability of peripheral target tissues to respond normally to insulin) is a common condition experienced at old age and often associated with obesity." (PMID 33946356, 2021). "Substantial literature implicates insulin in the regulation of 11βHSD1, and it has been inferred that altered insulin signaling underlies dysregulation of 11βHSD1 in obesity." (PMID 33270115, 2021). "Increased mIndy levels are associated with obesity and insulin insensitivity in patients with non-alcoholic fatty liver disease (NAFLD)." (PMID 35822025, 2021). "Four out of the five observational studies we reviewed support that Vit D level is significantly associated with the following components of MetS: obesity and BMI, dyslipidemia, BP, and insulin and glucose metabolism." (PMID 34589329, 2021). "Evidence shows that breakfast skipping is related to increased risk of obesity, insulin insensitivity, and higher risk of T2D compared with eating breakfast." (PMID 33918343, 2021). "Another study indicated that circadian rhythm and food intake interact to play a pivotal role in the development of adolescent obesity, perhaps because of the strong adverse association between glucose and insulin at nighttime." (PMID 34055002, 2021). "Obesity causes profound microbial changes, and gut microbes impact the host metabolism affecting inflammation, fat deposition, and insulin resistance." (PMID 34769060, 2021). "Several mechanisms have been associated with the obesity-related kidney disease that would mainly be summarized in three groups: the hemodynamic, the adipose tissue-related and the insulin resistance pathways." (PMID 33928108, 2021). "This suggests an ethnic-specific difference in the association between obesity, adipogenesis and insulin sensitivity." (PMID 33921645, 2021). "Hepatocellular carcinoma (HCC) cells display aberrant insulin signalling, and obesity and hyperinsulinaemia are associated with increased HCC risk." (PMID 34704005, 2021). "In rats, maternal exercise attenuated the lower skeletal muscle glucose uptake and insulin secretion caused by paternal obesity in female adult offspring." (PMID 33870263, 2021). "Anthropometric measurements, such as the body mass index (BMI) or waist–hip ratio, and circulating biomarkers, such as insulin or adiponectin, are currently used as general “obesity biomarkers” to identify disease risk due to obesity." (PMID 35050149, 2021). "The data herein demonstrate that increased insulin, acting via ghrelin cell–expressed IRs to reduce ghrelin secretion, is required for postprandial and obesity-associated reductions in plasma ghrelin." (PMID 34473648, 2021). "Obesity itself is described to promote inflammation, and it is associated with insulin and leptin resistance, which contribute to higher blood insulin and leptin levels." (PMID 34829950, 2021). "Bariatric surgery including duodenal-jejunal bypass surgery (DJB) improves insulin sensitivity and reduces obesity-associated inflammation." (PMID 33869077, 2021). "Obesity is an increasing concern among equine populations due to its potential association with a number of serious health conditions including insulin dysregulation and laminitis." (PMID 35051099, 2021). "IGF2BP2 rs4402960 is also associated with lower fasting insulin level and impaired β-cell function, both associated with obesity." (PMID 33568150, 2021). "LGS alleviated the obesity-associated inflammation and insulin resistant states associated with morbid obesity." (PMID 33981153, 2021). "Some evidence suggested that insulin and adrenal androgen play a central role in the association between accelerated skeletal maturation and overweight/obesity in children and adolescents." (PMID 32988365, 2020). "Obesity during pregnancy was associated with a decrease in AMPK-mediated signaling in the offspring leading to muscle insulin resistance." (PMID 32092940, 2020).
Obesity (continued). "To date, lower abundance of Desulfovibrio has been associated with obesity, blood pressure, insulin, and LDL." (PMID 32850910, 2020). "Using diet-induced obesity mice, CB2 receptor agonists were shown to be efficacious in reducing body weight and obesity-associated metabolic parameter, e.g., insulin." (PMID 32365865, 2020). "The only study to employ a machine learning (ML) approach to identify obesity risk factors in the QBB cohort revealed albumin, uric acid, insulin, and c-peptide as potential risk factors for obesity in Qatar." (PMID 33138081, 2020). "An integrative cross-omics analysis of DNA methylation sites have identified multiple CpGs for T2D, glucose and insulin homeostasis, and further showed the differential methylation explains at least 16.9% of the association between obesity and insulin." (PMID 32367290, 2020). "EGFL6 expression, which encodes an epidermal growth factor found to be enhanced in obesity and alters insulin action, was increased by 8.5-fold." (PMID 32826922, 2020). "On the other hand, the anti-oncogenic effect of statins in HCV patients is less evident, probably due to modification of metabolic syndrome, insulin-mediated cell proliferation, and obesity-associated inflammation." (PMID 32260179, 2020). "The “carbohydrate-insulin model” of obesity suggests that the primary defect lies in fat storage; excess fat storage causes obesity first which is followed by increased intake (hunger) and reduced activity." (PMID 32582754, 2020). "Parameters that are associated with cardiovascular risk factors, such as lipid profile, plasma glucose, serum insulin and HbA1C concentrations were evaluated at baseline and one year after the interventions in subjects with obesity, overweight and normal BMI." (PMID 32961973, 2020). "This deficiency has been implicated in the association between overweight/obesity and blunted insulin signaling via elevated intramuscular triglycerides." (PMID 32120832, 2020). "Dyslipidemia and chronic hyperglycemia caused by disturbance of insulin signaling in obesity can lead to glucolipotoxicity, which can play a pivotal role in AD." (PMID 32455946, 2020). "Previous studies have demonstrated that obesity is associated with downregulation of mitochondrial transcripts, lower ATP synthesis and decreased insulin sensitivity." (PMID 32695266, 2020). "Following CHF onset, obesity per se is associated with high skeletal muscle mass and preserved tissue ATP production, mitochondrial ROS production, redox state, cytokines and insulin signaling." (PMID 33158222, 2020). "Obesity was also reported to be associated with high carbohydrate intake due to continued elevation of blood insulin." (PMID 32046159, 2020). "Studies in whole body JNK1-null mice indicated that when mice are subjected to a high-fat diet (HFD), JNK1 is the most important isoform associated with obesity and plays a part in causing insulin resistance in insulin-sensitive tissues." (PMID 32183037, 2020). "The results of one study showed that plasma cholic acid was negatively associated with insulin sensitivity in a variety of subjects, including healthy volunteers, and patients with obesity and T2DM." (PMID 32405361, 2020). "Mutations in Lepr are associated with an obesity phenotype in mice and show elevated plasma levels of leptin, glucose, insulin and corticosterone." (PMID 31956894, 2020). "Interlekuin-18 deficient or IL-18 receptor knockout (Il18r1−/−) mice have obesity associated insulin resistance during high fat/protein diet." (PMID 32143623, 2020). "Cry1−/−Cry2−/− mice also have an increased sensitivity to HFD-induced obesity, which is associated with increased insulin secretion, elevated lipogenesis and TG accumulation in WAT and augmented proinflammatory cytokine levels." (PMID 33050331, 2020).
Obesity (continued). "This fat accumulation can directly contribute to CVDs through reduced insulin sensitivity, impaired insulin production, decreased glucose uptake in various tissues, and obesity-associated low-grade inflammation." (PMID 33330676, 2020). "Elevated plasma insulin levels and resistance to the metabolic effects of insulin are associated with obesity progression." (PMID 33105762, 2020). "A high-fat diet induces obesity-associated oxidative stress, neuronal insulin resistance, microglial activation, and neuroinflammation, which are considered important risk factors for neurodegeneration." (PMID 31963819, 2020). "Exposure to high-fat diet and obesity are associated with decreased insulin transport into the mammalian brain." (PMID 33291072, 2020). "This taxonomic group has been recently associated with improved insulin sensitivity in obese human subjects, alleviated obesity and metabolic dysfunctions in mice, and has been proven to negatively correlate with fasting blood glucose levels." (PMID 33125401, 2020). "Obesity-related IR causes reversible ß-cell dysfunction, which in turn affects the secretion of insulin." (PMID 33381036, 2020). "The complexity of the miRNAs network that links obesity with T2DM progression led us to focus this study on the effect caused by miR-27b modulation on hepatic insulin signaling." (PMID 33212990, 2020). "There are many reports of associations between gut microbes, obesity, and insulin sensitivity or blood glucose." (PMID 32860984, 2020). "Researchers have found that obesity promotes the expression of insulin and insulin-like growth factor-1 (IGF-1), causing the transformation of non-advanced colorectal polyps to advanced polyps and triggering recurrence." (PMID 32967679, 2020). "High glucose and fatty acid levels associated with obesity lead to increased reactive oxygen species (ROS) production, which causes insulin resistance in metabolic tissues." (PMID 32260306, 2020). "Despite the increase in the SMM, obesity is associated with an increased amount of type II muscle fiber, reduction in satellite cell activation, and insulin sensitivity, which impairs muscular regeneration." (PMID 33302887, 2020). "Studies on animals devoid of the TNF-α encoding gene with diet-induced obesity have shown significant improvement in insulin sensitivity." (PMID 33322719, 2020). "Here, we report that exposure to maternal obesity causes reduced proliferation of hypothalamic NPCs, fetal hypothalamic insulin resistance and neonatal alterations in the Notch signalling pathway." (PMID 32919096, 2020). "Obesity is associated with significant metabolic and endocrine abnormalities, including increased blood levels of growth factors such as insulin, insulin-like growth factor-1 (IGF-1) and leptin that can promote tumor cell growth and survival." (PMID 32549336, 2020). "In recent years, the notion of insulin being the initial factor causing obesity and its metabolic comorbidities has re-emerged." (PMID 32630256, 2020). "This is best seen in Cowden syndrome that occurs due to germline mutation of PTEN where insulin sensitivity is maintained despite obesity." (PMID 32582754, 2020). "Obesity, especially visceral adiposity, is a known independent risk factor for hypertension, although several studies suggest that insulin sensitization induced by CR are also associated with a decrease in SBP." (PMID 32587574, 2020). "In line with this, cross-sectional analyses in patients with obesity have shown positive associations between high circulating acetate and insulin sensitivity indices." (PMID 32012996, 2020). "In this study, we demonstrate that high BF% in women with obesity remission after RYGB is associated with reduced insulin sensitivity, higher TG concentration, and a more unfavorable body fat distribution, independent of BMI." (PMID 31832934, 2020).
Obesity (continued). "Our results showed that PP pulp has a protective effect against systemic abnormalities such as the fasting increase of both glycemia and insulin, indicating that PP treatment prevents the loss of glucose management associated with obesity." (PMID 32151028, 2020). "Adipose FAS mRNA expression is significantly associated with obesity, predominantly visceral fat accumulation, impaired insulin sensitivity, and circulating adipokines." (PMID 33312536, 2020). "PTEN loss in sporadic mutations also leads to obesity with retained insulin sensitivity, which is consistent with its position downstream of the insulin pathway, inhibiting PI3K/AKT/mTOR pathway." (PMID 32582754, 2020). "Rise in blood pressure (BP) is closely linked to an increase in measures of obesity, which, in turn, associate with a decline in insulin sensitivity and worsening of an atherogenic lipid profile." (PMID 32455627, 2020). "Obesity is associated with chronic low-grade inflammation leading to metabolic and cardiovascular diseases, but a subset of obese individuals is considered insulin sensitive (IS)." (PMID 33349270, 2020). "Circulating levels of adiponectin are inversely associated with obesity, insulin sensitivity, T2DM, and metabolic syndrome." (PMID 33192583, 2020). "We further examined the anti-obesity effects of scopolin in vivo by evaluating the serum concentrations of obesity-associated hormones such as leptin and insulin." (PMID 33218042, 2020). "Conversely, the leptin receptor-deficient db/db mouse model exhibits hyperleptinemia, obesity, hyperglycaemia, high insulin and decreased Prl in the serum and elevated hypophyseal Prl." (PMID 32183843, 2020). "Obesity was associated with higher systemic levels of fasting glucose and insulin, and with a pernicious lipid profile in both sexes." (PMID 32349335, 2020). "In experimental studies, bilirubin can improve the insulin sensitivity in leptin receptor-deficient and diet-induced mice with obesity." (PMID 32698889, 2020). "Obesity and a sedentary lifestyle are independently associated with changes in skeletal muscle that can reduce insulin sensitivity and increase hyperinsulinemia, contributing to elevated cardiovascular disease risk." (PMID 31628477, 2020). "The results of various BAT transplant studies have shown improvements in conditions associated with obesity, such as body weight and insulin sensitivity." (PMID 33227979, 2020). "As a result, the gut permeability was decreased and the endotoxemia caused by obesity was alleviated, with consequent improvement of the insulin resistance and glucose metabolism." (PMID 32218475, 2020). "Gamma glutamyl-hydrolase is an enzyme involved in folate metabolism, while lower folates levels were associated with reduced insulin sensitivity and obesity." (PMID 32635923, 2020). "Among other lines of evidence, the connection between obesity, hyperinsulinemia and enhanced cancer risk provides a biologically plausible rationale for a key role of insulin and the INSR in breast cancer initiation and/or progression." (PMID 32637033, 2020). "Increased plasma levels of CRP (p < 10 − 5), insulin (p < 10 − 4), and leptin (p < 10 − 7) showed dysmetabolic disorders associated with overweight/obesity." (PMID 32454823, 2020). "Firstly, the association and predictive value of non-insulin-based IR indices, obesity and lipid profiles for prediabetes were compared simultaneously; these are most common risk factors for prediabetes." (PMID 33059672, 2020). "We replicated findings that support insulin, glucose, and obesity as core determinants of cardiometabolic risk." (PMID 32218114, 2020). "The present findings are important because hyperinsulinemia is a risk factor for many, if not all, symptoms used to sort out the metabolic syndrome and elevated insulin levels have been suggested to be a causal factor for obesity." (PMID 31937343, 2020).